FKBP4 (FKBP prolyl isomerase 4)
Diseases named in the same sentence as FKBP4 in open-access papers (continued):
Sharing a sentence is not in itself a finding about the gene and the disease.
tumor (continued). "Subsequently, the function of FKBP4 in NSCLC cell lines and animals were investigated, and the relevant mechanisms of FKBP4 affecting tumor progression were also explored." (PMID 33354489, 2020). "Expression of the FK506 binding proteins FKBP4, FKBP6, and FKBP9, immunophilins known to interact with mTOR, was upregulated in DC-tumor fusions 5.3-, 6.7-, and 28-fold." (PMID 26605345, 2015). "A total of 15 genes (AIM1, ARF, CCNA1, MGMT, hMLH1, PGP9.5, S100A2, APC, RAR-β2, ER-α, ER-β, MCAM, VGF, FKBP4 and SSBP2) were analysed for promoter methylation using QMSP in 57 tumour samples, comprising 43 SEs and 14 NSEs, and 23 NT samples." (PMID 22068818, 2012). "Notably, AOC3, F8, and IL1A were found to be highly expressed in the normal group, while COA6, FKBP4, and LOXL2 were highly expressed in the tumours." (PMID 38577594, 2024). "MGMT, VGF, CCNA1 and FKBP4 are interesting, as they could be specific for tumours as all of the normal samples showed no methylation, and in addition, hMLH1 that had only one positive in normal." (PMID 22068818, 2012). "To test the involvement of FKBP4 in tumor growth in vivo, we established a MDA-MB-231 cell line-derived xenograft (CDX) tumor model in athymic mice, by injecting cells stably transfected with FKBP4-targeting shRNA, or with non-targeting shRNA." (PMID 31660083, 2019).
infection (3 papers, 2017 to 2021). The state of being infected such as from the introduction of a foreign agent such as serum, vaccine, antigenic substance or organism. "Infection of rSD20 in CEF cells was characteristic of regulated LMNA, HSPA2 and FKBP4." (PMID 28079188, 2017). "Of these, CD44, KDM1B, FKBP4, TEF, SYT4, SATB1 and PLCD1 are reported to be involved in the inflammatory reaction; for the remaining ten genes, there have been no reports concerning inflammation or infection." (PMID 34046191, 2021).
neurological diseases (2 papers, 2018 to 2021). "FKBP4, an element that is trans-regulated by MSTRG.55861, is relevant to steroid hormone receptor binding and transportation and to reproductive and neurological diseases." (PMID 35178025, 2021).
FKBP4 also shares sentences with these, for which no sentence is quoted: Anxiety (4 papers); glioblastoma (4); infertile (3); ovarian carcinoma (3); Parkinson disease (3); psychiatric disorder (3); tauopathy (3); cognitive deficits (2); dementia (2); female infertility (2); gastric cancer (2); head and neck cancer (2); invasive breast carcinoma (2); leukemia (2); male infertility (2); memory impairment (2); mood disorder (2); schizophrenia (2); sterility (2); abortion (1); acute stress disorder (1); adenovirus infection (1); alpha-synucleinopathies (1); amyloidosis (1); amyotrophic lateral sclerosis (1); anaplastic large cell lymphoma (1); anxiety disorder (1); Azoospermia (1); breast carcinoma in situ (1); carcinoma in situ (1).
A further 31 diseases each share a sentence with FKBP4 in 1 paper.